WFIKKN1 (WAP, follistatin/kazal, immunoglobulin, kunitz and netrin domain containing 1)
Description:
Protease-inhibitor that contains multiple distinct protease inhibitor domains. Probably has serine protease- and metalloprotease-inhibitor activity (By similarity).
Synonyms: C16orf12; WFIKKN; RJD2; WFDC20A
Tractability: Antibody: UniProt places it where antibodies can reach, with medium confidence; UniProt predicts a signal peptide or a membrane-spanning region; its Gene Ontology location is reachable by antibodies, with medium confidence.
Gene: Protein-coding gene on chromosome 16 (629,239 to 634,117, forward strand). Ensembl gene ENSG00000127578.
Subcellular location: Secreted
Gene Ontology:
Molecular function: protein binding; receptor antagonist activity; transforming growth factor beta binding; peptidase inhibitor activity; serine-type endopeptidase inhibitor activity
Biological process: negative regulation of transforming growth factor beta receptor signaling pathway; transforming growth factor beta receptor signaling pathway
Cellular component: extracellular region
Genetic constraint (gnomAD): Loss-of-function variants: 8 observed, 5.07 expected, observed/expected ratio (o/e) 1.58, 90% interval 0.86 to 1.94. That is too few expected variants to judge how well the gene tolerates losing a copy. Missense variants: 964 observed, 721.61 expected, observed/expected ratio (o/e) 1.34, 90% interval 1.27 to 1.41. Synonymous variants: 468 observed, 321.94 expected, observed/expected ratio (o/e) 1.45, 90% interval 1.35 to 1.57.
Homologues: Orthologues: chimpanzee WFIKKN1 (99% identical), macaque WFIKKN1 (97% identical), mouse Wfikkn1 (88% identical), dog WFIKKN1 (87% identical), pig WFIKKN1 (87% identical), rat Wfikkn1 (87% identical), guinea pig WFIKKN1 (85% identical), tropical clawed frog mettl26 (56% identical), zebrafish wfikkn2a (50% identical), zebrafish wfikkn2b (50% identical), Drosophila melanogaster CG7565 (10% identical), Caenorhabditis elegans Y55F3BR.2 (10% identical), and 2 more. Paralogues in human: WFIKKN2 (55% identical), AMBP (13% identical), SPINT1 (12% identical), KIAA0319L (12% identical), TFPI (11% identical), TFPI2 (10% identical), KIAA0319 (9% identical), WFDC8 (9% identical), SPINT2 (8% identical), EPPIN (8% identical), LRP11 (8% identical), SPINT4 (5% identical), and 1 more.
Diseases named in the same sentence as WFIKKN1 in open-access papers:
WFIKKN1 is named in the same sentence as 9 diseases in open-access papers, as found by Europe PMC text mining. Sharing a sentence is not in itself a finding about the gene and the disease. The quoted sentences say what the papers report.
endometrial cancer (1 paper, 2024). Primary or metastatic malignant neoplasm involving the endometrium (mucous membrane that lines the endometrial cavity). "Three proteins were associated with risk of prostate cancer: GP2, TSPAN1, and FLT3LG [1.29 (1.21–1.36), 1.14 (1.09–1.18), and 0.87 (0.82–0.92)] and three were associated with endometrial cancer: CHRDL2, KLK4, and WFIKKN1 [1.42 (1.21–1.65), 1.41 (1.20–1.65), and 1.42 (1.20–1.68)]." (PMID 38750076, 2024).
pulmonary hypertension (1 paper, 2024). Increased pressure within the pulmonary circulation due to lung or heart disorder. "Furthermore, the genes driving neutrophilic activity and TGF-β binding/skeletal muscle development (WFIKKN1 and ARG1) have been shown to be activated and involved in COPD, pulmonary hypertension, and chronic airway inflammation." (PMID 39346910, 2024).
Sciatica (1 paper, 2021). Pain in the lower back and hip radiating in the distribution of the sciatic nerve. "AZU1, BPI, TCF7L2, and WFIKKN1 were upregulated in sciatica patients, while ANGPTL4, CRP, EREG, FAM19A4, FGF1, LOC100129216, PLXNB1, RLN1, and RXFP2 were downregulated." (PMID 34925462, 2021). "To facilitate the diagnosis of sciatica by clinicians using the selected DEIRGs (RLN1, EREG, FAM19A4, WFIKKN1, and CRP), we constructed a nomogram model." (PMID 34925462, 2021).
tumor (2 papers, 2021 to 2025). "Statistical analysis showed significant tumor-specific upregulation of WFDC1, WFDC2, WFDC3, SLPI, PI3, and ANOS1 (P < 0.0001), while WFIKKN1 was notably downregulated in neoplastic tissues (P < 0.0001)." (PMID 40350979, 2025). "SLPI, WFDC2, WFIKKN2, and WFDC1 consistently showed low expression across tumor types, whereas WFDC5, WFDC3, and WFIKKN1 displayed heterogeneous expression profiles." (PMID 40350979, 2025). "FGF17, natriuretic peptide A (NPPA), SHC2, and WAP, follistatin/kazal, immunoglobulin, kunitz, and netrin domain containing 1 (WFIKKN1) was not expressed or at a minimal level in tumor tissues." (PMID 34335699, 2021).
cancer (1 paper, 2025). A tumor composed of atypical neoplastic, often pleomorphic cells that invade other tissues. "Conversely, SLPI, WFIKKN1, WFDC2, and WFDC1 demonstrated variable prognostic effects across cancer types, suggesting context-dependent, microenvironment-driven functional duality." (PMID 40350979, 2025).
WFIKKN1 also shares sentences with these, for which no sentence is quoted: Cachexia (1 paper); depression (1); prostate carcinoma (1); schizophrenia (1).